CD80 (CD80 molecule)
Diseases named in the same sentence as CD80 in open-access papers (continued):
Sharing a sentence is not in itself a finding about the gene and the disease.
keloid (1 paper, 2022). An irregularly shaped, elevated mark on the skin caused by deposits of excessive amounts of collagen during wound healing. "The expression of costimulatory molecules (CD28, CD80, CD86 and CD40L) in the immune microenvironment of keloids is higher than that in healthy people." (PMID 36012134, 2022). "Our results may suggest that the abnormal expression of costimulatory molecules (including CD28, CD86, CD80 and CD40L) may exist in the skin tissue of patients with keloids." (PMID 36012134, 2022).
Kidney Cyst (1 paper, 2023). Abnormal fluid filled sac within the kidney, either acquired or congenital. "Here, we explored the contribution of 2 immune checkpoints, PD-1|PD-L1 and CTLA-4|CD80/CD86, to kidney cyst growth using different orthologous ADPKD1 models with varying rates of PKD progression." (PMID 37345660, 2023).
leprosy (1 paper, 2015). Leprosy is a chronic infectious disease affecting primarily the skin and peripheral nervous system. "Given that B7.1 may utilize a compensatory costimulatory pathway, our previous work has shown that, regardless of the clinical form of leprosy, the addition of anti-CD86, but not anti-CD80, in cultured blood leukocytes led to a down regulation of T cell activation and the proliferative response." (PMID 25992795, 2015).
Lipedema (1 paper, 2020). Disorder of adipose tissue characterized by symmetric and bilateral enlargement of the lower extremities due to abnormal deposition of subcutaneous fat often in obese women. "Evaluation of M1 (CD80 and iNOS) and M2 (CD163 and TGFβ) polarization markers using qPCR revealed an increased CD163 expression (3.4-fold increase) in lipedema patients and as such a predominant M2 polarization profile." (PMID 32616854, 2020).
Listeria monocytogens infection (1 paper, 2019). "The decreased expression of CD86, I-Ab, CD80, and CD40 was also observed in Mettl3KO splenic DC after Listeria monocytogens infection." (PMID 31015515, 2019).
lupus erythematosus (1 paper, 2022). An autoimmune, connective tissue chronic inflammatory disorder affecting the skin, joints, kidneys, lungs, heart, and the peripheral blood cells. "Malfunctioning CD80 molecules are also involved in some pathological conditions, such as lupus erythematosus." (PMID 35682950, 2022).
Lymphadenopathy (1 paper, 2017). Enlargement (swelling) of a lymph node. "Albumin/AlbiCpG nanocomplexes upregulated the expression of costimulatory factor CD80 on DCs in draining LNs of C57BL/6 mice, despite accompanying lymphadenopathy." (PMID 29203865, 2017).
lymphoid neoplasm (1 paper, 2024). A neoplasm composed of a lymphocytic cell population which is usually malignant (clonal) by molecular genetic and/or immunophenotypic analysis. "Based on our results using the hamster anti-CD80 antibody, CD80 appears to be a specific marker for AML, whereas the other myeloid-associated antigens can be expressed in dogs with lymphoid neoplasms, as seen in this and other studies." (PMID 39224452, 2024). "We only had low numbers of certain types of lymphoid tumors in this study, such as CLL, and continued testing of the anti-CD80 antibody for specificity in AML would be worthwhile." (PMID 39224452, 2024). "Even though the expression pattern was different than expected, given that the antibody bound to neutrophils and monocytes in canine blood, we hypothesized that when using this antibody, CD80 would be a flow cytometric marker of AML, but not lymphoid neoplasms, in the dog." (PMID 39224452, 2024).
lymphopenia (1 paper, 2022). Reduction in the number of lymphocytes. "As a multi-targeted immunomodulator with anti-PD-L1 and B7 (CD80) costimulatory binding to reverse T cell exhaustion, it can be extrapolated that atezolizumab offers enhanced lymphopoiesis and count recovery, with mitigation of prolonged lymphopenia from RT." (PMID 35454808, 2022).
malignant hypertension (1 paper, 2021). Severe hypertension that is characterized by rapid onset of extremely high blood pressure and hypertension-mediated organ damage. "One might speculate that the enhanced expression of CTLA-4 and CD80 in malignant hypertension could point to an ongoing specific immune response." (PMID 34528115, 2021).
malignant thymomas (1 paper, 2026). "Although clinical studies on CD80 expression on CD62L+ pDCs are scarce, the findings of the study on its pro-tumorigenic effects in malignant thymomas provide a theoretical foundation for future targeted immunotherapy." (PMID 41497137, 2026).
mastocytoma (1 paper, 2014). A localized tumor composed of sheets of mast cells without atypia. "In our colleagues’ study, freshly isolated murine CD4+T cells were incubated with murine mastocytoma P815 cells transfectants expressing a similar level of either CD80 or CD86 in the presence of anti-CD3 mAb." (PMID 25344652, 2014).
megakaryoblastic leukemias (1 paper, 2024). "However, 2 acute megakaryoblastic leukemias had CD80+ cells." (PMID 39224452, 2024).
metastasis (1 paper, 2024). The spread or migration of cancer cells from one part of the body (where they first appeared) to another. "CD80 and CD86 expression on the cell surface was significantly positive in cases with Breslow thickness less than 2mm, no ulceration on the tumor surface, clinical stage I-II, and no lymph node metastasis in our study." (PMID 37614091, 2024).
metastatic colon tumor (1 paper, 2016). "Collectively, miR-18a treatment promoted induction of M1 macrophages (F4/80+IFNγ+ and F4/80+IL-12+) with upregulated co-stimulatory factors such as CD80, and iNOS while inhibiting M2 macrophages (F4/80+TGFβ+, F4/80+IL-10+) in the liver of metastatic colon tumor bearing mice." (PMID 27028860, 2016).
Miscarriage (1 paper, 2021). A pregnancy that ends at a stage in which the fetus is incapable of surviving on its own, defined as the spontaneous loss of a fetus before the 22th week of pregnancy. "Our previous animal investigation showed the positive role of CsA in improving the biological functions trophoblast cells and inducing maternal-foetal tolerance in miscarriage-prone mice with a high mRNA level of CD80/CD86." (PMID 33726772, 2021).
mucous membrane pemphigoid (1 paper, 2022). Mucous membrane pemphigoid is a bullous dermatosis characterized clinically by blistering of the mucous membranes followed by scarring, and immunologically by IgG, IgA and/or C3 deposits on the epidermal basement membrane. "Additionally, IL-13 exerts profibrotic and proinflammatory effects on the human conjunctival fibroblasts by up-regulating the expression of the T cell co-stimulatory molecules CD80, CD40, and CD154, suggesting a significant role in the pathophysiology in mucous membrane pemphigoid (MMP)." (PMID 35140724, 2022).
myositis (1 paper, 2025). "In a murine C‐protein‐induced myositis (CIM) model, treatment with CTLA4‐Ig or anti‐CD80/86 antibodies effectively suppressed myositis, suggesting its potential therapeutic feasibility for myositis." (PMID 41371271, 2025).
nasal polyp (1 paper, 2013). "In the nasal polyp tissues, DCs induce an imbalance in the proportion of the Th1/Th2 cells by causing the expression of CD80/CD86 to become unbalanced." (PMID 23737902, 2013).
Nephroblastoma (1 paper, 2024). An embryonal neoplasm characterized by the presence of epithelial, mesenchymal, and blastema components. "Finally, the results showed that there were significant differences in CD80, CD48, IDO2, CD276, CD28, and CD200R1 between both groups, which could be used as potential therapeutic targets for the treatment of nephroblastoma." (PMID 38526609, 2024).
oesophageal adenocarcinoma (1 paper, 2020). "TCM from oesophageal adenocarcinoma significantly enhanced CD54 (p < 0.001), CD80 (p < 0.001), HLA-DR (p = 0.001), CD86 (p < 0.001) and CD83 (p < 0.001) compared to LPS-induction in background media alone, cM199 (+)." (PMID 32552799, 2020). "In the LPS-stimulated setting, TCM from 2Gy irradiated oesophageal adenocarcinoma biopsies inhibited levels of CD54, compared to 0Gy patient-matched biopsies (p = 0.024), whereas, the levels of CD80, HLA-DR, CD86 and PD-L1 were not differentially altered." (PMID 32552799, 2020).
otitis media (1 paper, 2021). Inflammation of the anatomical structures of the middle ear, which is most often caused by an infectious process. "The phenotypes of B cells in the ear, nose, and throat, especially in patients with otitis media, were shown to be CD5low, CD23high, CD43low, B220high, sIgMlow, sIgDhigh, Mac-1low, CD80(B7.1)low, CD86(B7.2)low, and Syndecam-1low." (PMID 33801155, 2021).
pancreatic adenocarcinoma (1 paper, 2025). "Importantly, the activation of macrophages following radiation was not a model-specific phenomenon as spheroids of the pancreatic adenocarcinoma cell line Panc02-SIY combined with BMM0 also resulted in CD80 upregulation following radiation." (PMID 41417245, 2025).
pituitary adenomas (1 paper, 2021). "Aggressive pituitary adenomas demonstrated an increased expression of PD-L2, CD80, and CD86 in compared to that of normal human pituitary glands." (PMID 34745002, 2021). "There were significantly higher mRNA levels of PD-L2 (p < 0.0001), CD-80 (p = 0.0035), and CD-86 (p = 0.004) in aggressive pituitary adenomas." (PMID 34745002, 2021). "Our results demonstrating increased expression of PD-L2, CD80, and CD86 in aggressive pituitary adenoma samples provide a rationale for studying whether immune checkpoint blockade is effective for tumor control." (PMID 34745002, 2021). "In this study, we have found that the mRNA expression levels of the ligands for immune checkpoint receptors PD-1 and CTLA-4—namely, PD-L1 and PD-L2; CD80 and CD86, respectively— were all significantly higher in pituitary adenomas than in the normal human pituitary." (PMID 34745002, 2021). "Furthermore, the mRNA levels of CD80 and CD86 were significantly higher in the most aggressive subset of PAs compared to non-aggressive pituitary adenomas." (PMID 34745002, 2021). "The significance of increased CD80 and CD86 expression in pituitary adenomas has not been previously reported, but we hypothesize it predicts an increased reliance on CTLA-4 mediated pathway of tumor suppression." (PMID 34745002, 2021).
Pleural effusion (1 paper, 2021). The presence of an excessive amount of fluid in the pleural cavity. "This study shows that CD16+ monocytes isolated from pleural effusion of TPE patients exhibit a more mature phenotype than CD16- monocytes, such as costimulatory molecules CD40, CD80, CD86 and HLA-DR." (PMID 34237073, 2021).
reovirus infection (1 paper, 2021). "Reovirus infection caused an upregulation of HLA/H-2, CD80, and Fas, which was most evident in the PC3 and TRAMP-C2 cell lines." (PMID 33665363, 2021).
retinoblastoma (1 paper, 2016). A malignant tumor that originates in the nuclear layer of the retina. "Retinoblastoma cell could upregulate CD80 and CD86 on DCs, and stimulated allogeneic T cells proliferation." (PMID 27556503, 2016).
silicosis (1 paper, 2018). Silicosis is a respiratory disease caused by breathing in (inhaling) silica dust. "The subsequent mechanistic study found that the expressions of MHC-II, CD80/86 and IL-12, which are the key molecules that connect DCs and Th cells, changed dynamically in the experimental silicosis rat model." (PMID 35541981, 2018). "In summary, our study demonstrated that DCs accumulated in lung tissues of silica dust exposure rats and regulated the polarization of Th1/Th2 cells via CD80, CD86, MHC-II and IL-12 expressions, indicating that DCs may play a critical role in modulating immune homeostasis during silicosis in rats." (PMID 35541981, 2018).
skin inflammation (1 paper, 2025). "These previously unidentified findings further elaborate the emphasis of cis PD-L1:CD80 interactions on migratory DCs as a primary target for PD-L1 antibodies across several models of skin inflammation, which leads to a significant decrease of CD80, unlike PD-1 antibody therapy." (PMID 39879305, 2025).
skin reaction (1 paper, 2006). "IFNβ enhances the expression of CD80, SCYB10 (IP-10) and SCYA2 (MCP1) in situ at sites of injection, leading to chemotaxis of lymphocytes and monocytes in the lesions of skin reaction." (PMID 16709257, 2006).
soft tissue sarcoma (1 paper, 2024). A malignant neoplasm arising from muscle tissue, adipose tissue, blood vessels, fibrous tissue, or other supportive tissues excluding the bones. "Further analysis illustrates the potential association between immune evasion markers (PD-L1 and CD80) and tumor metastasis in soft tissue sarcoma." (PMID 38360860, 2024).
Splenomegaly (1 paper, 2009). Abnormal increased size of the spleen. "This again is contrary to MHV-68 infections in the absence of CD40, CD40L or CD80/CD86, where splenomegaly and/or viral load during latency amplification were either similar or lower." (PMID 19621080, 2009).
steatosis (1 paper, 2019). Increased lipid within the cytoplasm of cells. "Interestingly, mice deficient in the co-stimulatory molecule CD80/86 (B7.1/B7.7) showed increased liver steatosis when fed a HFD, a similar phenotype as observed in our CD40fl/flCD11ccre mice." (PMID 31604965, 2019).
synovial sarcoma (1 paper, 2021). "Taken together, sunitinib treatment of both bone and synovial sarcoma cells induced a significant upregulation of CD80, CD86, CD83 and CCR7 which are essential for full DC maturation." (PMID 33717062, 2021).
T cell neoplasms (1 paper, 2024). "None of the tumor cells in dogs with T cell neoplasms were labeled with the anti-CD80 antibody; however, the cells were CD11b+ (2/22, 9%) or CD11c+ (6/19, 32%) in low numbers of dogs." (PMID 39224452, 2024).
thymic lymphomas (1 paper, 2015). "Furthermore, by gating of the CD11c+ DCs cell population using flow cytometry analysis, we confirmed that the Ia, CD86, CD80, CCR7, CD40 and IL-12 proteins of CD11+ DCs were all down-regulated in thymic lymphomas." (PMID 25923834, 2015).
thymus atrophy (1 paper, 2015). Acquired diminution of the size of the thymus associated with wasting as from death and reabsorbtion of cells, diminished cellular proliferation, decreased cellular volume, pressure, ischemia, malnutrition, reduced function or malfunction, or hormonal changes. "Deletion of these cells in FSP1-TK transgenic mice caused thymus atrophy due to the loss of TECs, especially mature medullary TECs (MHCIIhigh, CD80+ and Aire+)." (PMID 26445893, 2015).
toxoplasmosis (1 paper, 2015). A parasitic disease contracted by the ingestion or fetal transmission of toxoplasma gondii. "Since IL-1β is expressed in the intestine following T. gondii infection, and there are TLR ligands produced by the parasite or by commensal bacteria, it is possible that these signals contribute to the group 3 ILC CD80 expression seen during toxoplasmosis." (PMID 26010337, 2015). "Although the RORγt+ ILC population was markedly reduced during toxoplasmosis, some of the cells that remained at 9 days post-infection expressed MHC II and CD80." (PMID 26010337, 2015).
tuberculosis (1 paper, 2019). A chronic, recurrent infection caused by the bacterium Mycobacterium tuberculosis. "In addition, CD80 has a role in enhancing the anti-tuberculosis immunity." (PMID 31480266, 2019).
uveal melanoma (1 paper, 2019). A melanoma derived from melanocytes of the uveal tract. "Collectively, our data indicate that Mel202/DR1/CD80 uveal melanoma vaccine cells maintain the activation of various subtypes of CD4+ T cells." (PMID 30956760, 2019). "Previously, we have generated cell-based vaccines that consist of primary uveal melanoma cells genetically modified to express major histocompatibility class II (MHC II) alleles syngeneic to the recipient and the costimulatory molecule CD80 (B7.1)." (PMID 30956760, 2019). "Therefore, the ICAM-1/LFA-1 interaction plays an important role in the activation of CD4+ T cells by Mel202/DR1/CD80 uveal melanoma vaccines." (PMID 30956760, 2019). "Finally, Mel202/DR1/CD80 uveal melanoma vaccine cells expressed the intercellular adhesion molecule 1 (ICAM-1) that was pivotal for CD4+ T cell activation via lymphocyte function-associated antigen 1(LFA-1)." (PMID 30956760, 2019). "Since the antigens presented by the uveal melanoma vaccine cells are unknown, we determined TCR-Vβ usage of vaccine-activated CD4+ T cells upon repetitive stimulation with Mel202/DR1/CD80 vaccines." (PMID 30956760, 2019).
vitamin D deficiency (1 paper, 2021). A nutritional condition produced by a deficiency of VITAMIN D in the diet, insufficient production of vitamin D in the skin, inadequate absorption of vitamin D from the diet, or abnormal conversion of vitamin D to its bioactive metabolites. "The data here show that vitamin D deficiency was associated with decreased CD80 and IFN-γ in PCOS (both p<0.05), and IL-12 (p<0.05) in both PCOS and controls." (PMID 33716989, 2021). "Vitamin D deficiency was associated with decreased CD80 and IFN-γ in PCOS and IL-12 in both groups (p<0.05)." (PMID 33716989, 2021).